GDF15 (growth differentiation factor 15)
Diseases named in the same sentence as GDF15 in open-access papers (continued):
Sharing a sentence is not in itself a finding about the gene and the disease.
atherosclerosis (continued). "Growth differentiation factor‐15 (GDF‐15) is a strong and independent predictor of mortality and disease progression in patients with atherosclerosis alongside with carotid‐intimal media thickness (CIMT)." (PMID 35846052, 2022). "This is evaluated by measurement of CIMT (as a biomarker of subclinical atherosclerosis) by ultrasonography and was positively correlated with dyslipidemia and elevated serum GDF‐15, which is detected by ELISA." (PMID 35846052, 2022). "GDF15 is upregulated by various cardiovascular events associated with oxidative stress, as reported in coronary heart diseases (CHD), HF, and atherosclerosis." (PMID 34445593, 2021). "To further determine the correlation of GDF-15 with atherosclerosis, we compared GDF-15 expression in macrophages residing in blood vessels." (PMID 34539804, 2021). "In this study, we aimed to explore the role of GDF-15 in lipoprotein accumulation and inflammatory response in atherosclerosis." (PMID 34539804, 2021). "GDF-15, released in senescent ECs, contributes to the pathogenesis of atherosclerosis via its pro-senescent activity, implicating endothelial loss of function." (PMID 34571994, 2021). "GDF-15 can be upregulated in endothelial cells and reflect endothelial activation, which is an important progression of atherosclerosis." (PMID 34394348, 2021). "To determine the effect of GDF-15 on atherogenesis, we studied the effect of GDF-15 on proinflammatory cytokines, chemokines, and matrix protein, which all are correlated with atherosclerosis initiation and development in the presence of oxLDL." (PMID 34539804, 2021). "To explore the relationship of GDF-15 with atherosclerosis, we recruited 65 healthy people and 101 patients with coronary atherosclerosis." (PMID 34539804, 2021). "In conclusion, this study showed that GDF-15 suppressed atherosclerosis by inhibiting lipid accumulation and decreasing the expressions of IL-6, IL-8, MCP-1, and MMP-9 in macrophages." (PMID 34539804, 2021). "The serum GDF-15 level in atherosclerosis patients and healthy people and the expression and location of GDF-15 in the aorta atheromatous plaque in mice were detected first." (PMID 34539804, 2021). "To determine the relationship of GDF-15 with atherosclerosis, we compared the serum GDF-15 levels in patients with atherosclerosis and healthy people." (PMID 34539804, 2021). "Little is known about the regulation and mechanism of autophagy, especially in respect of GDF-15 and the pathogenesis of atherosclerosis." (PMID 34571994, 2021). "To determine the real role of GDF-15 in atherosclerosis, we detected the effect of GDF-15 on lipoprotein accumulation and inflammatory response in oxLDL-induced macrophages." (PMID 34539804, 2021). "Other vascular cells can express GDF15 in vitro when subjected to stress but the importance of this in atherosclerosis in vivo is uncertain." (PMID 32310257, 2020). "In agreement, another study in mice demonstrates that GDF15 is involved in the progression of atherosclerosis by regulating apoptotic cell death and IL-6 inflammatory response." (PMID 32757036, 2020). "The pleiotropic biological role of GDF15 is still a matter of much debate, and there is evidence for both anti‐inflammatory and pro‐inflammatory roles such as in the context of atherosclerosis (Emmerson, Duffin, Chintharlapalli, & Wu, 2018)." (PMID 32157804, 2020). "Consistently, overexpression of GDF-15 in macrophages significantly attenuated atherosclerotic lesions in the apoE knockout mouse model of atherosclerosis." (PMID 33115406, 2020). "Clinical studies have demonstrated that GDF15 is elevated in patients with subclinical vascular dysfunction, atherosclerosis, and in those who subsequently develop the complications of atherosclerosis." (PMID 32310257, 2020).
atherosclerosis (continued). "This analysis of 694 ever-smokers without clinical CVD at enrollment to the COPDGene cohort demonstrates that GDF-15 independently contributes to subclinical atherosclerosis in COPD." (PMID 28245821, 2017). "In a study by Bonaterra and colleagues about GDF-15 knockout mice, it was shown that GDF-15 deficiency protects mice against atherosclerosis." (PMID 26075263, 2015). "In conclusion, this is the first study evaluating the effects of GDF-15 in advanced stages of atherosclerosis." (PMID 23800095, 2013). "This study was performed to evaluate the effects of GDF-15 in an established mouse model of advanced atherosclerosis." (PMID 23800095, 2013). "This is the first study that demonstrates a protective role of GDF-15 in advanced atherosclerosis and macrophage accumulation, possibly due to the reduced expression of adhesion molecules." (PMID 23800095, 2013). "In vivo and in vitro experimentation suggests that MIC-1/GDF15 probably plays an anti-inflammatory role, notably in mouse models of arthritis and atherosclerosis." (PMID 22514681, 2012). "Many participants were relatively young and without CVD, reducing the probability of detecting GDF-15-atherosclerosis association." (PMID 41597417, 2026). "One of the first studies investigating GDF-15 in atherosclerosis was conducted in 2011." (PMID 41590509, 2026). "In chronic inflammatory diseases, disease activity itself may influence circulating GDF-15, limiting the capacity to estimate the exact contribution of inflammation to GDF-15-atherosclerosis relationship." (PMID 41597417, 2026). "Our recent study revealed that GDF15 deficiency did not influence atherosclerosis progression in either male or female mice injected with AAV8-PCSK9-D377Y." (PMID 40837873, 2025). "Strikingly, 10 genes exhibited shared dysregulation in both aging and atherosclerosis, including Vcam1, Apoe, Gdf15, Timp1, Cxcl12, Hspd1, Serpine1, App, Eln, and Hif1a, suggesting their potentially critical roles in the atherosclerosis driven by aging in HGPS mice." (PMID 41209003, 2025). "Some studies suggest that GDF15 may promote atherosclerosis development, while others indicate that it could be protective." (PMID 40837873, 2025). "The broad involvement of GDF15 in diverse cardiovascular and systemic conditions, involving inflammation, metabolic dysregulation, atherosclerosis, and endothelial impairment, likely underpins its strong prognostic association with adverse limb events in PAD patients, as observed in our study." (PMID 40806859, 2025). "The role of GDF15 in atherosclerosis is not completely understood." (PMID 41303556, 2025). "A. Heduschke and co-authors investigated the effects of GDF-15 on autophagy using an in vitro human atherosclerotic macrophage model and an in vivo GDF-15-deficient (GDF-15−/−) apolipoprotein E knockout (apoE−/−) mouse model of experimental atherosclerosis." (PMID 38396781, 2024). "In the early phases of atherosclerosis, GDF-15 promotes chemotaxis of macrophages to plaques." (PMID 37548881, 2024). "The exact relationship between GDF-15 and atherosclerosis is not fully understood." (PMID 37548881, 2024). "GDF-15 contributes to both the onset and advancement of atherosclerosis." (PMID 38791250, 2024). "The mechanism underlying the positive association between serum GDF-15 levels and atherosclerosis at different ages is not yet clear." (PMID 38396781, 2024). "Previous studies have shown that GDF-15 is increased in hypertension and atherosclerosis." (PMID 38396781, 2024). "Studies suggest that GDF-15 is involved in the initiation and progression of atherosclerosis." (PMID 39329916, 2024). "As GDF-15 expression on ECs has been shown to be induced by C-reactive protein (CRP) and atherosclerosis is chronic inflammation, future studies should assess CRP levels to confirm the association between GDF-15 and the degree of atherosclerosis." (PMID 38396781, 2024).
atherosclerosis (continued). "It appears that GDF-15 may be involved in the onset and progression of atherosclerosis and could relate to subclinical atherosclerosis." (PMID 38396781, 2024). "Whether GDF-15 is a mediator in inflammation and atherosclerosis or a response to inflammatory processes involved in vascular injury must be clarified." (PMID 39780955, 2024). "Physical conditions that increase serum GDF-15 levels might lead to the development of atherosclerosis, but GDF-15 might prevent atherosclerosis." (PMID 37371667, 2023). "Therefore, suggesting that GDF15 prevents atherosclerosis in the ApoE knockout mice, which is nowadays the most used murine model for atherosclerosis because of its displayed hypercholesterolemic status." (PMID 36992609, 2023). "In addition, thyroid function, which regulates energy balance, can also influence both serum GDF-15 concentrations and atherosclerosis as evaluated by CIMT." (PMID 37371667, 2023). "Circulating levels of GDF-15 may be a biomarker of subclinical atherosclerosis in patients with psoriasis." (PMID 37485268, 2023). "CCR2 is a key chemokine receptor for monocyte recruitment at earlystage of atherosclerosis and is decreased by GDF-15–deficient macrophages.The direct interaction of GDF-15 with the chemokine receptor CCR2 functionsuggests that the GDF-15-induced macrophage mobility modulates the CCR2 response." (PMID 39077481, 2023). "The mechanism underlying the positive association between serum GDF-15 concentration and atherosclerosis among older individuals with normal weight has not been clarified yet." (PMID 37371667, 2023). "Because atherosclerosis is an inflammatory process, it has been hypothesized that GDF-15 may be used as a valid marker of prognosis in patients with atherosclerosis-related CVD." (PMID 36676179, 2023). "Overall, the role of GDF-15 in the influence of inflammation on atherosclerosis appears to be multifaceted, suggesting that GDF-15 may serve as a predictor of plaque stability." (PMID 37900593, 2023). "Since low-grade inflammation is a known risk factor for atherosclerosis and CKD, clarifying the association between serum GDF-15 concentrations and atherosclerosis as evaluated by CIMT in a comparatively healthy population can help estimate the risk for developing age-related atherosclerosis." (PMID 37371667, 2023). "GDF-15 has been reported to add prognostic information in several CV disorders including myocardial infarction (MI), atherosclerosis, aortic stenosis, pulmonary hypertension and ischemic stroke as well as in HFrEF and more recently also in HF with preserved EF (HFpEF)." (PMID 34611778, 2022). "Elevated GDF15 has been shown to promote inflammation and angiogenesis, implying that GDF15 may play an important role in the pathogenesis of atherosclerosis." (PMID 36444166, 2022). "Altogether, whether GDF-15 constitutes a causative risk factor or a CVD biomarker remains to be defined, although mounting evidence suggests a direct role for GDF-15 in accelerating atherosclerosis." (PMID 36093162, 2022). "Atherosclerosis and inflammation are related to growth differentiation factor-15 (GDF15)." (PMID 35160008, 2022). "GDF15 may provide the dual effects of pro-inflammatory and anti-inflammatory function in the development and progression of atherosclerosis, depending on the different progression stage and pathophysiological environment." (PMID 35683420, 2022). "In this context, higher GDF15 in T2DM patients with atherosclerosis and thrombotic complications could be a compensatory mechanism against reverse oxidative and inflammatory‐induced thrombotic disorders." (PMID 36444166, 2022). "Thus, our data suggested that the expression of GDF-15 was upregulated in atherosclerosis produced mainly by macrophages." (PMID 34539804, 2021). "GDF15 levels increase in response to inflammatory conditions and this has been shown to contribute to endothelial dysfunction, vascular inflammation, metabolic syndrome and atherosclerosis pathogenesis." (PMID 33812333, 2021).
atherosclerosis (continued). "It has been suggested that GDF-15 plays an important role in the pathogenesis of atherosclerosis." (PMID 34830700, 2021). "This study indicated that GDF-15 may suppress atherosclerosis and plaque formation by inhibiting lipoprotein accumulation and inflammation activation." (PMID 34539804, 2021). "We also measured GDF-15 in atherosclerosis plaques from the ApoE−/− mice model of atherosclerosis." (PMID 34539804, 2021). "Previous studies suggested GDF-15 might play an important role in inhibiting the occurrence of atherosclerosis, but the concrete role and mechanism of GDF-15 in atherosclerosis remain unclear." (PMID 34539804, 2021). "Since age is a well-established classic risk factor of cardiovascular disease, it could be hypothesized that higher concentrations of GDF15 along with age contribute to the development of atherosclerosis in patients with alopecia areata." (PMID 34830700, 2021). "Therefore, we used different analyses (activity assays, TEM) and autophagy-relevant markers (ATG5, p62) to investigate and verify the influence of GDF-15 on the autophagic pathway in atherosclerosis." (PMID 34571994, 2021). "Although the results of this study are inconsistent with some existing studies, and the role of GDF-15 in atherosclerosis is still controversial, which needs further research and elucidation, GDF-15 still has the potential to become a target for the diagnosis and treatment of atherosclerosis." (PMID 34539804, 2021). "Thus, our results showed that GDF-15 suppressed proinflammatory response induced by oxLDL and attenuated atherosclerosis initiation as well as progression by downregulating TLR4." (PMID 34539804, 2021). "In mice with atherosclerosis, GDF-15 was highly expressed in the core of plaque and macrophages." (PMID 34539804, 2021). "The differing associations observed between GDF-15 and diverse subclinical markers of atherosclerosis in our study add to the on-going discussion of whether GDF-15 is a marker or a maker of CVD36,37." (PMID 34728734, 2021). "GDF-15 has been hypothesized to play a crucial role in cardiovascular diseases, especially in the development of atherosclerosis." (PMID 34571994, 2021). "And then one ApoE−/− mouse model of atherosclerosis was used to explore the effects of GDF-15 on oxidized low-density lipoprotein (oxLDL) accumulation, atherosclerosis-related gene expression, and lipid accumulation-related protein expression in mouse macrophages." (PMID 34539804, 2021). "On the one hand, elevated GDF15 has been shown to promote inflammation and angiogenesis, implying that GDF15 may play an important role in the pathogenesis of atherosclerosis." (PMID 32222153, 2020). "Other inflammatory cells or markers that are involved in the pathology of both PE and atherosclerosis or sex-specific markers involved in atherosclerosis such as growth differentiation factor 15 may be of specific interest." (PMID 32085575, 2020). "Similar results were reported in an ApoE(−/−) mouse model of atherosclerosis, indicating that GDF15 may play an anti-inflammatory role in the process of atherosclerosis." (PMID 32222153, 2020). "GDF15 is related to inflammation, renal function, atherosclerosis, and cardiovascular mortality." (PMID 31466396, 2019). "Besides the heart, the effect of GDF15 on atherosclerosis has also been evaluated by several groups, but these results are contradictory." (PMID 30542297, 2018). "We demonstrate that in COPD subjects free of clinical CVD, subclinical atherosclerosis (measured as CAC on ungated HRCT) is frequent; and that GDF-15 contributes, independently of common cardiovascular risk factors and measures of COPD severity or phenotype, to its presence and severity." (PMID 28245821, 2017).
atherosclerosis (continued). "Whilst MIC-1/GDF15 serum levels are elevated in inflammatory conditions like atherosclerosis and rheumatoid arthritis, current evidences from animal models suggest that it may be anti-inflammatory, neurotrophic and neuroprotective." (PMID 25867953, 2015). "We think that GDF-15 might be a novel strong biomarker in cardiovascular diseases like heart attack or atherosclerosis." (PMID 26075263, 2015). "Regulation of apoptosis through GDF-15 may be a therapeutic strategy to control atherosclerosis and plaque progression." (PMID 26273671, 2015). "In the present study, we tested whether GDF-15 alters lesion size and lesion composition in an advanced stage of atherosclerosis." (PMID 23800095, 2013). "GDF-15 is expressed by myocardial cells at ischemia, injury, reperfusion and cardiac dysfunction, and also by monocytes/macrophages involved in the atherosclerosis process." (PMID 24312445, 2013). "In detail, the diminished progression of atherosclerosis, indicated by decreased lumen stenosis in GDF‐15−/−/apoE−/− mice, may be the consequence of alterations in apoptotic processes, proliferation, and number of MФ or SMC in atherosclerotic lesions." (PMID 23316317, 2012). "In this context it would be of interest for future studies to address the issue of whether GDF‐15 overexpressing mice reveal an enhanced lesion development and progression in experimental atherosclerosis despite their lower body weight." (PMID 23316317, 2012). "A deeper understanding of GDF15’s role in atherosclerosis and vascular dysfunction could ultimately inform the development of targeted treatments, enhancing our capacity to understand and address the overlapping pathophysiology of PAD, CAD, and CVD to improve cardiovascular outcomes." (PMID 40723863, 2025). "Additionally, circulating levels of GDF15 have been related to atherosclerosis and CV disease." (PMID 40076667, 2025). "Thus, high GDF-15 levels might amplify the influence of fast eating speed on atherosclerosis development." (PMID 39019981, 2024). "Since mitochondrial stress increases GDF-15 levels, GDF-15 promotes VSMC proliferation, oxLDL has been shown to be associated with GDF-15 action, and GDF-15 levels correlate with CIMT, GDF-15 may be associated with the degree of atherosclerosis." (PMID 38396781, 2024). "In the present study, we found that serum GDF-15 concentration is significantly positively associated with atherosclerosis as evaluated by CIMT, even among older individuals with normal weight in the general population who have normal serum thyroid hormone concentrations." (PMID 37371667, 2023). "Altogether, it appears that the precise impact of GDF15 in dyslipidaemia, especially in the context of atherosclerosis, remains to be elucidated in order to ascertain whether this molecule can represent a useful pharmacological target to combat the occurrence of dyslipidaemia in MetS." (PMID 36992609, 2023). "However, there have been no reports about the association between serum GDF-15 concentration and atherosclerosis as evaluated by carotid intima-media thickness (CIMT) among the general population." (PMID 37371667, 2023). "Additionally, GDF15 exerts overall protective effects against atherosclerosis." (PMID 36992609, 2023). "Aging, BMI, and thyroid activity might not affect the association between GDF-15 concentrations and atherosclerosis as evaluated by CIMT." (PMID 37371667, 2023). "Growth differentiation factor-15 (GDF15) or macrophage inhibitory cytokine-1, a member of the transforming growth factor-b superfamily, is related to inflammation, chronic vascular diseases, cancer, ischemia, and atherosclerosis, behaving as a lesion-induced factor." (PMID 35160008, 2022). "Conversely, GDF15 may play a protective role in atherosclerosis by attenuating macrophage accumulation via the downregulation of adhesion molecules and has also been identified as a good prognostic serum biomarker in chronic heart failure and myocardial infarction." (PMID 33812333, 2021).